RUNX1 (RUNX family transcription factor 1)
Diseases named in the same sentence as RUNX1 in open-access papers (continued):
Sharing a sentence is not in itself a finding about the gene and the disease.
cancer (continued). "In human cancers, the Runx1 gene has been reported to be mutated, as somatic point mutations in myelodysplasia and chromosomal translocation in acute myeloid leukemia." (PMID 34440820, 2021). "The RUNX1-deficient HT29 cancer cells showed lower capability for liver metastasis and formation of replacement vessel co-option lesions comparing to control." (PMID 34376784, 2021). "Previous report have demonstrated that lncRNA-NEF and runt-related transcription factor 1 (RUNX1) are associated with EMT in cancer." (PMID 32154257, 2020). "Recently, CBFB and RUNX1 mutations have been identified as drivers in a variety of cancer types, including breast, ovarian, and prostate cancer." (PMID 31061501, 2019). "In both early and aggressive cancer cell types, loss of Runx1 expression paralleled decreases of the epithelial marker E-cadherin, while the mesenchymal marker Vimentin was highly expressed only in the MCF10CA1a cells." (PMID 28407681, 2017). "Repression, overexpression, and/or deregulated functioning of Runx1 have been shown to cause cancers." (PMID 28407681, 2017). "The gene set specific for Runx1 loss was subjected to Ingenuity Pathway Analysis which revealed significant associations with cancer and in particular with proliferation, apoptosis and differentiation of lymphocytes." (PMID 27056890, 2016). "Both mutations and increased expression of Runx1, a required factor for hematopoiesis, are associated with breast and lung cancer tumors." (PMID 27634876, 2016). "Caspase-2 cleaved one of these proteins, the cancer-associated transcription factor Runx1, although with relatively low efficiency." (PMID 27919034, 2014). "More interestingly, RUNX1 was significantly associated with poorer recurrence-free survival and cancer-specific survival for patients with triple negative disease (p = 0.046 and p = 0.022 respectively)." (PMID 24967588, 2014). "This can be explained by a possibility in which RUNX1-mutantbreast cancer originates from ER+ luminal MECs andRunx1 disruption alone actually leads to the loss of thecell-of-origin of such cancer." (PMID 25415051, 2014). "These events include CDKN2A deletion and MYC amplification in immortalization, HRAS activation in transformation, PIK3CA activation in the formation of malignant tumors, and RUNX1 deletion associated with poorly-differentiated malignant tumors." (PMID 20169162, 2010). "The three highly homologous human RUNX TFs (RUNX1, 2, and 3) have been implicated in developmental processes and, notably, in cancer." (PMID 21203558, 2010). "These genetic changes include CDKN2A deletion and MYC amplification in immortalization, HRAS activation in transformation, PIK3CA activation in the formation of malignant tumors, and RUNX1 deletion associated with poorly-differentiated malignant tumors." (PMID 20169162, 2010). "We applied SEUSS to overexpress the library in myelogenous leukemia cells and analyzed single-cell transcriptional readouts to identify functionally distinct groups of RUNX1 mutations, characterize their effects on cellular programs, and study implications for cancer." (PMID 38968069, 2024). "We checked the significant germline mutations, the mutations which could cause effects on cancer development or progression, only very three gene mutations were detected, including RUNX1, CDKN2A, and ERCC5." (PMID 39105897, 2024). "In addition, Runt-associated transcription factor-1 (RUNX1) is overexpressed in cancer cells that replace lesions." (PMID 38737903, 2024). "RUNX1 is implicated in diverse prognostic outcomes across various cancer types." (PMID 38430423, 2024). "Previous studies have suggested that RUNX1 may be associated with the development of cancers such as acute leukemia, renal cell, colorectal, breast, uterine and ovarian adenocarcinomas." (PMID 38886545, 2024). "Moreover, in the Catalogue of Somatic Mutations in Cancer, RUNX1 is included in the top 20 mutated genes." (PMID 36766786, 2023).
cancer (continued). "Consistent with the KOPTK1 observations, RUNX1-KO led to ∼50% reduction of H3K27ac levels in all three cell lines suggesting that RUNX1 associated loss of genome-wide H3K27ac density may be generalizable across cancer types." (PMID 37213235, 2023). "Genetic alterations in CBFB and RUNX1 are associated with many types of human diseases and cancers." (PMID 37760803, 2023). "Our previous pan-cancer analysis predicted that RUNX1 mutations and JAK2 may have a synthetic lethal interaction." (PMID 37581927, 2023). "Interestingly, we observed a lower expression of cleaved PARP-1 and ARP2/3 in the hepatocytes of metastatic lesions that were generated from RUNX1-deficient HT29 cancer cells in comparison to those that were generated by control HT29 cancer cells." (PMID 35267627, 2022). "Additionally, the increased level of RUNX1 was linked to the activation of oncogenic signaling pathways in human cancers, suggesting a potential role of RUNX1 among cancer therapeutic targets." (PMID 35534796, 2022). "THY1, SCG2, and RUNX1 play risk factors in various cancer types." (PMID 35498539, 2022). "We hypothesized that cancer-associated drugs would display higher modeled ΔΔG values for their expected/known targets and lesser ΔΔG values for RUNX1." (PMID 36090034, 2022). "Importantly, RUNX1 expression was positively correlated with cancer-associated fibroblasts (CAFs) in more than 30 different cancers." (PMID 36077723, 2022). "Here, we propose that structural molecular modeling and docking studies for RUNX1 in the presence of DNA, and/or drugs, may facilitate assessment of the potential impact of RUNX1 cancer associated mutations in AML." (PMID 36090034, 2022). "Altered expression of RUNX1 is associated with many other cancers." (PMID 29245924, 2017). "However on univariate analysis, positive RUNX1 expression was significantly associated with poorer cancer-specific survival in the ER− (P<0.05) and triple negative (ER−/PR−/HER2−) (P<0.05) groups of patients." (PMID 24967588, 2014). "RUNX1 (a TF required for differentiation of blood cells) is another example of a lineage-specific TF that is preferentially mutated in AML (~9% of cases) compared with other cancer types (mutated in less than 4% of cases for other cancer types)." (PMID 25473436, 2014). "As RUNX1 is a pioneer transcription factor and master regulator implicated in multiple cancer types, we hypothesized that mutations affecting its interactions with transcriptional co-factors would manifest as changes to expression of RUNX1 target genes, resulting in functional diversity in cancer." (PMID 38968069, 2024). "Therefore, we hypothesised that RUNX1 expression in the cancer cells may be linked to Ang1 expression in the neighbouring hepatocytes." (PMID 36330498, 2022). "Consequently, mis-regulation of RUNX1 is associated with cancers." (PMID 36430923, 2022). "Indeed, breaks at cRSSs in cancer driver genes were found to be a predominant cause for cancer progression in ETV6/RUNX1 ALL, and our LAM-HTGTS experiments suggest the ESC could play a role in causing some of these breaks." (PMID 31333681, 2019).
cancer (continued). "Consistently, our pathway analysis revealed that target genes of RUNX1 participate in key pathways, which have been previously reported in this type of cancer, such as Pathways in cancer, WNT signaling pathways and the BDNF signaling pathway." (PMID 41020879, 2025). "On the other hand, in this work we focused on the transcription factor RUNX1 because the dysregulation of transcription factors is a key event in cancer." (PMID 41020879, 2025). "We also identified SOD1 and BACH1, involved in regulating cellular responses to oxidative stress, and transcription factor RUNX1 that can regulate cancer cell proliferation and metastasis." (PMID 40018643, 2025). "BRD4 commonly associates with cancer-maintenance genes (e.g. MYC, RUNX1) that are decorated with high-level acetylation, which leads to selective cancer dependency on BRD413." (PMID 39651888, 2025). "Genes activated by RUNX1 through the regulation of chromatin loops are enriched for GO terms related to cancer cell growth and migration, implying that RUNX1 plays a broad role in enhancer–promoter interactions to regulate leukemic gene expression." (PMID 39450904, 2025). "In recent years, the carcinogenic effect of RUNX1 has attracted increasing attention in the field of cancer, including non-small-cell lung cancer, renal cell carcinoma, ER-negative breast cancer, endometrial cancer, etc." (PMID 38419056, 2024). "More interestingly, in CRC, RUNX1 is overexpressed and has been identified as a potent driver in colorectal tumorigenesis; conversely, RUNX1 is reported to work as an anti-cancer factor in gastrointestinal malignancies." (PMID 38778047, 2024). "Here, the hematopoietic transcription factor Runx1 is discovered as a key regulator of MMT in cancer patients." (PMID 37967345, 2024). "The percentages of RUNX1+ cells, CD8+RUNX1+T/CD8+T cells, and CD103+CD8+RUNX1+T/CD8+T cells were all higher in cancer tissues than in paracancer tissues." (PMID 39822248, 2024). "Further study showed that in VC, RUNX1 is highly expressed in the cancer cells, which induces the expression of transforming growth factor β1 (TGF-β1)and Ang-1 in the neighboring liver parenchyma." (PMID 38737903, 2024). "RUNX1 manifests dichotomous roles, reflecting the complexity of its regulatory mechanisms in cancer development." (PMID 39309442, 2024). "The data collectively suggests that RUNX1 acts as a key regulatory node in the establishment of drug resistance across diverse types of cancer, thereby offering multiple therapeutic avenues for intervention." (PMID 38430423, 2024). "KEGG analysis of the H_S group indicated that RUNX1 is primarily involved in cancer-related pathways, including cancer transcription misregulation pathways and tight junctions." (PMID 39272372, 2024). "Accordingly, the use of PDGFs/PDGFRs antagonists in combination with the therapeutic strategy for targeting RUNX1 seems to be the practicable approach in the cancers therapy." (PMID 38419056, 2024). "RUNX1 protein has been shown to have oncogenic or inhibitory effects by activating or suppressing target genes in a variety of cancers 22,23." (PMID 38886545, 2024). "Meanwhile, an increasing number of studies have revealed the pro- or anti-cancer roles of RUNX1 in solid tumors." (PMID 38430423, 2024). "RUNX1 critically influences the stem-like properties of cancer cells, with evidence pointing to its role in the stabilization of leukemia stem cell attributes in a pluripotent model." (PMID 38430423, 2024). "To establish the broader oncogenic potential of RUNX1 across various cancers, we analyzed its expression patterns utilizing TCGA data through computational platforms TIMER and GEPIA." (PMID 39309442, 2024). "Within this complex biological process, the transcription factor RUNX1 has emerged as a multifaceted regulator, exhibiting both pro-angiogenic and anti-angiogenic activities depending on the cancer type." (PMID 38430423, 2024).
cancer (continued). "RUNX1 expression features in normal issues and cancers, and the mechanism of action of RUNX1 in many cancer types has highlighted the potential of RUNX1 as a biomarker for cancer." (PMID 37760803, 2023). "In particular, the apoptotic signaling pathway was highlighted in the RUNX1 KD cancer cells’ enrichment pathways and chosen for further investigation." (PMID 38057816, 2023). "RUNX1 has been identified as a critical transcription factor regulating multiple biological processes of cancer." (PMID 36776876, 2023). "RUNX1 knockdown resulted in the proliferation, invasion and migration abilities of cancer cell lines (SKOV3, OVCAR3) significantly reduced than control cell lines." (PMID 38057816, 2023). "In the present study, we first performed a pan-cancer analysis of the expression of RUNXs and then demonstrated that RUNX1, RUNX2, and RUNX3 are highly expressed in various cancers." (PMID 36321611, 2023). "The expression of RUNX1 in 15 of 32 cancers was changed relative to that in the corresponding normal tissues, including increased expression in 13 cancers and decreased expression in 2 cancers." (PMID 36321611, 2023). "Intriguingly, RUNX1 acts as a tumor suppressor or as a dominant oncogene of the EMT process based on different types of cancer." (PMID 37367670, 2023). "Treated with Ro5-3335, a RUNX1-CBFβ interaction inhibitor, the level of p-FOXO1Ser256 and Bcl-2 were significantly changed in control cancer cell lines (SKOV3, OVCAR3), meanwhile the expression level of FOXO1 was almost unchanged after Ro5-3335 treatment." (PMID 38057816, 2023). "The need for further tissue studies to clarify the molecular mechanisms in the interaction between RUNX1 and CAFs is highlighted separately for different cancer types." (PMID 38275375, 2023). "Although misregulation of RUNX1 was first identified in blood-related cancers, many researchers have now identified its role in many different types of cancer, especially tumors of epithelial origin." (PMID 37760803, 2023). "Ectopic upregulated RUNX1 has been pinpointed as contributing to the carcinogenesis of various cancer cells." (PMID 37367670, 2023). "Runt-related transcription factor 1 (RUNX1) is a transcription factor involved in the pathogenesis of cancer by regulating cellular processes, including apoptosis and cell proliferation." (PMID 36759729, 2023). "Many research works discovered the WNT signaling pathway plays a key role in multiple RUNX1-regulated cancers." (PMID 38057816, 2023). "RUNX1 has been demonstrated in various cancer studies to inactivate the TGF-β1/SMAD signaling pathway." (PMID 37546862, 2023). "RUNX1 has been shown to be upregulated in most cancers compared with normal tissues, in agreement with the results of our study." (PMID 37612452, 2023). "RUNX1-mediated modulations to hallmarks of cancers consist of cancer stem cell-renewal and self-renewal, cell proliferation, angiogenesis, tumor metastasis, the resistance of chemotherapies, and inhibition of cell apoptosis, resulting in carcinogenesis." (PMID 37444447, 2023). "Although studies on RUNX1 were initially explored in blood-related cancers, its roles has now been gradually reported and identified in studies of many solid tumors, especially those of epithelial origin." (PMID 37760803, 2023). "Some of the most prevalent included known pediatric cancer fusions RUNX1::RUNX1T1 (15% AML participants), KMT2A::MLLT3/MLLT10 (12% AML), TCF3::PBX1 (4.4% ALL), and ETV6::RUNX1 (2.4% ALL)." (PMID 37323575, 2023). "Recent studies have suggested that RUNX1 and Foxp3 can synergistically inhibit cancer cell proliferation and apoptosis, suppressing the growth and spread of cancer cells by inhibiting metabolic pathways and Ras or other signaling pathways." (PMID 37342563, 2023).
cancer (continued). "At the same time, RUNX1 also acts as an oncogene and tumor suppressor gene in epithelial tumors, and its role in various cancers has attracted more and more attention." (PMID 37760803, 2023). "It will be of interest to determine if the cooperative role of RUNX1 with oncogenic (co)factors in T-ALL cells extends to other cancers through synergistic partnerships with additional transcription factors." (PMID 37213235, 2023). "RUNX1 plays a crucial, pivotal role in many cancer types, raising concerns about RUNX1 as a biomarker for cancer." (PMID 38057816, 2023). "RUNX1 indicates particular tissue specificity and does either inhibit or promote substantive malignant tumors derived from different tissue sources." (PMID 38057816, 2023). "MLF1 treatment upregulates the level of C/EBPα by suppressing Trib1 or RUNX1-ETO, which causes the inactivation of myeloid-derived suppressor cells (MDSCs) with potent antitumor responses across different tumor models and cancer patients." (PMID 36814822, 2023). "Another major finding of our study was that RUNX1 expression correlated with diverse oncogenic signaling pathways in different cancers." (PMID 35534796, 2022). "RUNX1 is widely expressed in mammalian cells and is reported to be dysregulated in many human cancers." (PMID 35534796, 2022). "While RUNX1 mis-regulation has been originally explored in blood-related cancers, its role has now been identified in many other types of cancers, particularly tumors of epithelial origins." (PMID 36430923, 2022). "We used these sections to identify the correlation between RUNX1 expression in the cancer cells and neutrophil infiltration." (PMID 36330498, 2022). "Accordingly, the expression of RUNX1 in the cancer cells promotes cancer cell motility through its target genes including the genes of ARP2/3 complex subunits." (PMID 36330498, 2022). "The expression levels of Ang1 were significantly increased in the hepatocytes upon co-culturing with control cancer cells, whereas silencing RUNX1 in the cancer cells significantly impaired Ang1 expression in the hepatocytes." (PMID 36330498, 2022). "Overall, our results confirmed the governing role of RUNX1 in cancer cell-driven phenotype modifications in hepatocytes, which facilitated hepatocyte displacement." (PMID 35267627, 2022). "Our IF results also suggested that the presence of RUNX1 in the cancer cells was essential to induce motility and EMT in the adjacent hepatocytes in vitro." (PMID 35267627, 2022). "First, we observed a correlation between RUNX1 expression and prognosis in 8 of the 13 types of cancer using the PrognoScan database." (PMID 35534796, 2022). "RUNX1 participates in different hallmarks of cancer, such as the developmental differentiation of multiple human cell lines." (PMID 36142846, 2022). "The cancer cells of vessel co-opting CRCLM lesions were characterized by a high expression of RUNX1 that correlated with the upregulation of its target genes, including TSP1." (PMID 35267627, 2022). "The observation results indicate that up-regulation of RUNX1 is a common event in CRC specimens and is closely related to cancer metastasis, and that RUNX1 promotes the EMT of CRC cells by activating Wnt/β-catenin signaling." (PMID 35836256, 2022). "Overexpression of Runt-Related Transcription Factor-1 (RUNX1) in cancer cells of the replacement lesions, which is mediated by TGF-β1 and thrombospondin 1 (TSP1), enhances cell motility to achieve vessel co-option." (PMID 36430910, 2022). "We first analyzed the mRNA expression levels of RUNX1 across human cancers and paired normal samples by utilizing the HG-U133 microarray (GPL570 platform) of the Gent2 database." (PMID 35534796, 2022). "We found similar levels of neutrophil infiltration in vessel co-opting and angiogenic lesions that were generated by RUNX1-silenced HT29 cancer cells." (PMID 36330498, 2022).